SUPT6H (SPT6 homolog, histone chaperone and transcription elongation factor)
Description:
Histone H3-H4 chaperone that plays a key role in the regulation of transcription elongation and mRNA processing. Enhances the transcription elongation by RNA polymerase II (RNAPII) and is also required for the efficient activation of transcriptional elongation by the HIV-1 nuclear transcriptional activator, Tat. Besides chaperoning histones in transcription, acts to transport and splice mRNA by forming a complex with IWS1 and the C-terminal domain (CTD) of the RNAPII subunit RPB1 (POLR2A). The SUPT6H:IWS1:CTD complex recruits mRNA export factors (ALYREF/THOC4, EXOSC10) as well as histone modifying enzymes (such as SETD2), to ensure proper mRNA splicing, efficient mRNA export and elongation-coupled H3K36 methylation, a signature chromatin mark of active transcription. SUPT6H via its association with SETD1A, regulates both class-switch recombination and somatic hypermutation through formation of H3K4me3 epigenetic marks on activation-induced cytidine deaminase (AICDA) target loci. Promotes the activation of the myogenic gene program by entailing erasure of the repressive H3K27me3 epigenetic mark through stabilization of the chromatin interaction of the H3K27 demethylase KDM6A.
Synonyms: KIAA0162; SPT6H; SPT6; emb-5
Tractability: Antibody: the Human Protein Atlas places it where antibodies can reach. PROTAC: ubiquitination databases record sites on it; its protein half-life has been measured.
Gene: Protein-coding gene on chromosome 17 (28,661,929 to 28,702,682, forward strand). Ensembl gene ENSG00000109111.
Subcellular location: Nucleus
Subcellular location (Human Protein Atlas): Cytosol; Nucleoplasm; Plasma membrane
Pathways (Reactome):
Gene expression (Transcription): Formation of RNA Pol II elongation complex; RNA Polymerase II Pre-transcription Events; RNA Polymerase II Transcription Elongation
Gene Ontology:
Molecular function: histone binding; protein binding; RNA binding; nucleosome binding; DNA binding; nucleic acid binding
Biological process: transcription elongation by RNA polymerase II; transcription elongation-coupled chromatin remodeling; nucleosome organization; regulation of isotype switching; regulation of muscle cell differentiation
Cellular component: nucleoplasm; transcription elongation factor complex; nucleus
Genetic constraint (gnomAD): Loss-of-function variants: 11 observed, 228.61 expected, observed/expected ratio (o/e) 0.0481, 90% interval 0.029 to 0.08. The upper end of that interval is the gene's LOEUF score, 0.08, which puts it in group 1 of 6, group 1 being the genes least tolerant of losing a copy. Missense variants: 1,420 observed, 2,319.7 expected, observed/expected ratio (o/e) 0.61, 90% interval 0.58 to 0.64. Synonymous variants: 762 observed, 845.79 expected, observed/expected ratio (o/e) 0.9, 90% interval 0.85 to 0.96.
Homologues: Orthologues: macaque SUPT6H (99% identical), chimpanzee SUPT6H (99% identical), guinea pig SUPT6H (99% identical), rabbit SUPT6H (99% identical), dog SUPT6H (98% identical), rat Supt6h (98% identical), mouse Supt6 (98% identical), pig SUPT6H (92% identical), tropical clawed frog supt6h (87% identical), zebrafish supt6h (82% identical), Drosophila melanogaster Spt6 (49% identical), Caenorhabditis elegans emb-5 (34% identical).
Diseases named in the same sentence as SUPT6H in open-access papers:
SUPT6H is named in the same sentence as 20 diseases in open-access papers, as found by Europe PMC text mining. Sharing a sentence is not in itself a finding about the gene and the disease. The quoted sentences say what the papers report.
breast carcinoma (4 papers, 2021 to 2025). "SUPT6H is associated with DNA repair in glioblastoma cancer stem-like cells (GSCs) and estrogen-regulated transcription in breast cancer cells." (PMID 34202873, 2021). "Further overlaps with breast cancer cell dependencies revealed SUPT6H and RAD21, along with their respective protein systems, HOST:37 and HOST:861, as potential biomarkers." (PMID 39838298, 2025). "It was further shown that SUPT6H protein levels are inversely correlated with breast cancer malignancy." (PMID 33199825, 2021). "For example, suppressor of Ty 6 homolog (SUPT6H), a histone chaperone and transcription elongation factor, was found to be required for estrogen-mediated transcription and maintenance of chromatin structure in breast cancer cells, likely through interaction with RNF40 and regulation of H2Bub1." (PMID 33199825, 2021).
breast tumours (1 paper, 2020). "Like H2Bub1 levels, SUPT6H levels were shown to decrease over the course of breast tumorigenesis, with more malignant breast tumours with a worse prognosis demonstrating less SUPT6H and H2Bub1." (PMID 33233707, 2020).
cystic kidney disease (1 paper, 2012). A congenital or acquired kidney disorder characterized by the presence of renal cysts. "Analyses indicated 13 genes, in addition to Nek8 and Ift20 within this area that could potentially result in cystic kidney disease, namely: RGD1309077Phf12, Flot2, Spag5, Sdf2, Supt6h, Proca1, Traf4, Sarm1, Nlk and Ksr1." (PMID 22899815, 2012).
osteosarcoma (1 paper, 2021). A usually aggressive malignant bone-forming mesenchymal neoplasm, predominantly affecting adolescents and young adults. "For this purpose, we integrated the AID sequence at the SPT6 locus (SUPT6H) in the U2OS human osteosarcoma cell line by CRISPR-Cas9-mediated genome editing." (PMID 34233157, 2021).
cancer (9 papers, 2012 to 2024). A tumor composed of atypical neoplastic, often pleomorphic cells that invade other tissues. "The posttranscriptional mechanism of SUPT6H should be clarified to facilitate its use as a cancer therapeutic target in the future." (PMID 34202873, 2021). "A cDNA array analysis revealed no significant changes in the expression of SUPT6H in gastrointestinal cancer cells, suggesting that posttranscriptional regulation is a key step in cancer progression." (PMID 34202873, 2021).
tumor (8 papers, 2012 to 2026). "Our functional study showed the tumor proliferative function in gastrointestinal cancer cells (HCT116, SUIT-2, OE33 and KYSE70 cells), suggesting that the tumor-progressive property of SUPT6H is regulated by the posttranslational regulation." (PMID 34202873, 2021). "While the human Ahnak gene was initially cloned from tumor cells and later characterized as a tumor suppressor, chemotherapy-induced p11/AnxA2/Supt6h complex is known to facilitate Oct4-mediated gene transcription and thereby is involved in chemotherapy-induced breast cancer stem cell enrichment." (PMID 36046712, 2022).
SUPT6H also shares sentences with these, for which no sentence is quoted: glioblastoma (3 papers); infection (3); bladder cancer (1); Burkitt lymphoma (1); colon cancer (1); COVID-19 (1); esophageal cancer (1); glioma (1); Hyperkeratosis (1); lentivirus infection (1); malignant glioma (1); neurodevelopmental disorder (1); pancreatic tumours (1); psoriasis (1).